INPP4B (inositol polyphosphate-4-phosphatase type II B)
Diseases named in the same sentence as INPP4B in open-access papers (continued):
Sharing a sentence is not in itself a finding about the gene and the disease.
breast carcinoma (continued). "Similarly, knockdown of INPP4B in thyroid, mammary epithelial cell and breast cancer cell lines provided an advantage for anchorage-independent growth." (PMID 36993823, 2023). "The repurposing of existing FDA-approved NSAIDs and anti-parasitic drugs that suppress Wnt/β-catenin signaling is emerging as a more promising clinical strategy, such as pyrvinium which was selectively cytotoxic to INPP4B-overexpressing ER+ breast cancer cells in combination with 4-OHT." (PMID 37471270, 2023). "However, INPP4B expression is increased in a subset of ER+ breast cancers where it paradoxically promotes cell proliferation and tumor growth." (PMID 37471270, 2023). "Here, we examined the effect of these candidate Wnt inhibitors on MCF-7 ER+ breast cancer cell viability after 48 h treatment in monolayer culture, and whether INPP4B expressing cells were more sensitive to these drugs." (PMID 36612130, 2022). "Altogether, these findings suggest that pyrvinium may be a potential drug candidate for ER+ breast cancer cells with high INPP4B expression." (PMID 36612130, 2022). "We previously generated and validated MCF-7 and T47D human immortalized PIK3CA-mutant ER+ breast cancer cell lines with stable ectopic GFP-INPP4B overexpression, in order to model the effects of increased INPP4B expression as we described in a subset of ER+ breast tumors." (PMID 36612130, 2022). "Collectively, our findings suggest that repurposing pyrvinium to inhibit Wnt/β-catenin signaling may be an effective strategy to selectively target ER+ breast cancers with high INPP4B expression." (PMID 36612130, 2022). "Here, we examined whether increased INPP4B expression alters the sensitivity of ER+ breast cancer cells to current standard-of-care therapies, and investigated the efficacy of Wnt therapeutics." (PMID 36612130, 2022). "Therefore, pyrvinium has the potential to be repurposed as a therapeutic for ER+ breast cancers that exhibit increased INPP4B expression." (PMID 36612130, 2022). "More recently, INPP4B was identified as a bona fide marker of ER-positivity in human breast cancer." (PMID 36612130, 2022). "However, INPP4B overexpressing ER+ breast cancer cells were more sensitive than control cells to pyrvinium, an FDA-approved drug that suppresses Wnt/β-catenin signaling, and to 4-OHT-pyrvinium combination treatment." (PMID 36612130, 2022). "However, INPP4B-overexpressing ER+ breast cancers cells were more sensitive to pyrvinium treatment when grown in monolayer culture, and combined 4-OHT-pyrvinium treatment significantly enhanced INPP4B-overexpressing ER+ breast cancer cell death." (PMID 36612130, 2022). "INPP4B acts as a tumour suppressor gene in breast cancer cells and prostate cancer cells." (PMID 33879096, 2021). "Furthermore, breast cancers in general upregulate the PI3K signaling pathway through the expression of constitutive active or amplification of PIK3CA and deletion of PTEN or INPP4B or Akt mutations." (PMID 34917906, 2021). "Therefore PIK3CA-mutant ER+ breast cancers, which exhibit increased INPP4B expression, display a gene expression profile consistent with increased Wnt/β-catenin signaling." (PMID 34035258, 2021). "In addition to PTEN, inositol polyphosphate-4-phosphatase type IIB (INPP4B) can counteract PI3KCA signaling, and loss of its genetic locus has been reported in breast cancer." (PMID 34298731, 2021). "The PI3K/AKT/mTOR pathway is frequently deregulated in breast cancer by different mechanisms, leading to increased PI3K activity and/or loss of PI3K inhibitory functions as well as mutation in tumor suppressor genes like INPP4B and PTEN phosphatases." (PMID 34298731, 2021). "INPP4B expression is lost in triple-negative breast cancers, however, its emergence as a potential oncogene in other cancers led us to examine its relative expression and function in ER+ breast cancers." (PMID 34035258, 2021).
breast carcinoma (continued). "Through pair-wise and block-wise interactive OS analyses on SNPs of INPP4B and RAD50, we identified two disease-associating blocks, each containing five SNPs (INPP4B) and two SNPs (RAD50), respectively, which synergistically affect breast cancer clinical outcome." (PMID 31872854, 2020). "Both RAD50 and INPP4B are crucial to maintain genomic integrity and prevent tumorigenesis, and co-deletion of both genes commonly co-occurs in many types of cancers including breast cancer." (PMID 31872854, 2020). "Importantly, the differential expression of the selected proteins reflects key clinical parameters defining breast cancer subtypes: ER status (INPP4B); tumor grade (CDK1); and HER2 status (ERBB2)." (PMID 31315058, 2019). "However, emerging studies show that INPP4B also has tumour-promoting properties in cancers including acute myeloid leukemia, colon cancer, melanoma and breast cancer." (PMID 31695845, 2019). "Similarly, loss of PTEN or the 4-phosphatase INPP4B results in accumulation of PI34P2 at the plasma membrane in MCF10a breast cancer cells and loss of both PTEN and INPP4B substantially enhanced Akt activity and invadopodia formation." (PMID 31131274, 2019). "Recent studies have indicated an association between high INPP4B expression and SGK3 phosphorylation levels in PIK3CA-mutant breast cancers and melanoma, in which INPP4B-mediated activation of SGK3 enhances cell proliferation and promotes anchorage-independent cell growth." (PMID 29343273, 2018). "INPP4B knockdown promotes AKT-mediated breast cancer cell growth and proliferation." (PMID 28082369, 2017). "Inositol polyphosphate-4-phosphatase, type II (INPP4B), a tumor suppressor, has a reduced expression in prostate and breast cancers compared to normal tissues, yet its roles in BCa remain unclear." (PMID 25277204, 2014). "This is based on the fact that loss of heterozygosity at the INPP4B locus correlates with ovarian cancer and aggressive hormone receptor-negative basal-like breast cancer as well as poor patient survival." (PMID 24500884, 2014). "INPP4B LOH is frequently observed in hormone receptor negative breast cancers and loss of INPP4B protein is associated with loss of hormone receptors and basal-like breast cancers." (PMID 21487159, 2011). "Although INPP4B does not appear to be hormonally regulated in breast cancer cells, its expression appears to be tightly associated with hormone receptor status." (PMID 21487159, 2011). "Similarly, INPP4B knockdown increased the proliferation of human basal-like breast cancer cells." (PMID 36993823, 2023). "Therefore, Wnt inhibition using pyrvinium may be an effective strategy for treating human breast cancers with high INPP4B expression." (PMID 36612130, 2022). "Thus, we also assessed whether INPP4B overexpression confers sensitivity of PIK3CA-mutant ER+ breast cancer cells to alpelisib." (PMID 36612130, 2022). "To further identify the synergies between INPP4B and RAD50 on clinical consequences at the genetic level, we are motivated to identify the relevant disease-associating SNPs that affect the expression of each gene and are collectively prognostic of the clinical outcome of breast cancer patients." (PMID 31872854, 2020). "Indeed, INPP4B tumour suppressor function was initially identified in breast cancer." (PMID 28082369, 2017). "In addition, INPP4B is preferentially lost in basal breast cancers." (PMID 21646685, 2011). "Altered expression of biomarkers such as INPP4B and CD45 in the LTT group and breast cancer samples suggests a potential role in BC development, warranting further investigation." (PMID 40729351, 2025). "Studies indicated a correlation between high INPP4B expression and SGK3 phosphorylation levels in breast cancer and melanoma cells, in which INPP4B overexpression triggered phosphorylation and activation of SGK3, not AKT." (PMID 36993823, 2023).
breast carcinoma (continued). "INPP4B overexpression increased activated-β-catenin and Wnt target gene expression in PIK3CA-mutant ER+ human breast cancer cells." (PMID 37471270, 2023). "INPP4B was described as an oncogene by SGK3 activation in melanoma, breast cancer, and colon cancer." (PMID 35075772, 2022). "Indeed, our results indicate that INPP4B-overexpressing ER+ breast cancers cells exhibit increased sensitivity towards LGK-974 or PRI-724 in combination with 4-OHT, suggesting that combining Wnt therapeutics with an endocrine therapy may be a potential strategy for this breast cancer subset." (PMID 36612130, 2022). "Here, we identify that INPP4B promotes late endosome/lysosome formation and trafficking that activates Wnt/β-catenin signaling in PIK3CA-mutant ER+ breast cancer." (PMID 34035258, 2021). "We therefore propose INPP4B facilitates crosstalk between PI3K and Wnt/β-catenin signaling pathways on a late endosome signaling hub in PIK3CA-mutant ER+ breast cancer." (PMID 34035258, 2021). "Together, these findings are consistent with an interpretation that INPP4B promotes Wnt/β-catenin signaling and thereby the proliferation of PIK3CA-mutant ER+ breast cancer cells via enhanced late endosome formation." (PMID 34035258, 2021). "We report PIK3CA-mutant ER+ breast cancers exhibit increased INPP4B mRNA and protein expression and INPP4B increased the proliferation and tumor growth of PIK3CA-mutant ER+ breast cancer cells, despite suppression of AKT signaling." (PMID 34035258, 2021). "Here, the authors show that INPP4B enhances proliferation and growth of PIK3CA-mutant ER+ breast cancers by promoting PI3Kα-dependent late endosome formation and trafficking that leads to the activation of Wnt/β-catenin signalling." (PMID 34035258, 2021). "INPP4B increased the proliferation and tumor growth of PIK3CA-mutant ER+ breast cancer cells, despite reduced AKT activation." (PMID 34035258, 2021). "We demonstrate INPP4B overexpression enhances the proliferation and tumor growth of PIK3CA-mutant ER+ breast cancer cell lines, despite concurrent AKT signaling suppression." (PMID 34035258, 2021). "The miRs that target the tumor-suppressive protein phosphatases including PTEN, PHLPP2 and INPP4B, which elevate the PI3K pathway activity in luminal breast cancer." (PMID 32751711, 2020). "We have previously demonstrated that INPP4B and RAD50 collectively affect breast cancer survival at the transcriptional and translational levels." (PMID 31872854, 2020). "INPP4B resides in the PI3K/Pten/mTOR pathway which is a complex network that controls cell proliferation and survival and is deregulated in over 70% of breast cancers." (PMID 31872854, 2020). "In breast cancer, SGK3 is amplified and acts as PIK3CA oncogenic effector in a INPP4B phosphatase-dependent manner." (PMID 32296634, 2020). "Many candidate genes emerged to be related to this breast cancer subtype, such as AKT1, AKT3, INPP4B, and EGFR." (PMID 30630526, 2019). "The suppressive function of INPP4B, akin to that of PTEN, was initially identified in breast cancer, and later confirmed in ovarian and prostate cancers." (PMID 29343273, 2018). "Four of these five patients—two with cervical cancer, one with breast cancer, and one with germline cancer—had at least two molecular alterations involving the PI3K/AKT/mTOR pathway, including STK11 and INPP4B." (PMID 32914004, 2018). "Sixty-seven breast cancer PDX including 42 TNBC, 17 ER+ and 8 HER2+ tumors, were stained with primary antibodies against PTEN and INPP4B." (PMID 27374081, 2016). "By analogue, INPP4B is known to activate SGK3 and drive tumourigenesis in a subset of breast cancers with low Akt." (PMID 26573229, 2015). "Nevertheless, a significant inhibitory effect of INPP4B expression on in vivo NPC tumor growth in nude mice was observed, similar to that previously reported in melanoma and breast cancers." (PMID 25126743, 2014).
breast carcinoma (continued). "INPP4B overexpression did not affect the sensitivity of ER+ breast cancer cells in monolayer culture to current standard-of-care therapies including 4-OHT or alpelisib." (PMID 36612130, 2022). "Here, using cell viability assays, we report that INPP4B overexpression does not affect the sensitivity of ER+ breast cancer cells to standard-of-care treatments including the anti-estrogen 4-hydroxytamoxifen (4-OHT) or the PI3Kα inhibitor alpelisib." (PMID 36612130, 2022). "4-OHT treatment also impeded GFP-INPP4B and GFP-vector T47D cell viability comparably, suggesting that INPP4B overexpression does not affect ER+ breast cancer cell sensitivity to anti-estrogen therapy." (PMID 36612130, 2022). "In three-dimensional (3D) culture models, pyrvinium selectively reversed the increased size of INPP4B-overexpressing ER+ breast cancer spheroids in the presence and absence of 4-OHT." (PMID 36612130, 2022). "Using 3D culture models, we demonstrated that pyrvinium selectively reduced the size of INPP4B-overexpressing ER+ breast cancer spheroids in the presence and absence of 4-OHT." (PMID 36612130, 2022). "Although Hrs knockdown did not affect the size or weight of GFP-vector tumors, the enhanced growth of GFP-INPP4B tumors was suppressed by Hrs depletion, indicating that INPP4B promotes the proliferation and tumor growth of PIK3CA-mutant ER+ breast cancer cells in an Hrs-dependent manner." (PMID 34035258, 2021). "Similarly, studies have suggested that the oncogenic roles of the miR-181 family in breast cancer cells is achieved through targeting PHLPP2 and INPP4B phosphatases, thus accelerating cancer cell cycle progression and proliferative potential." (PMID 34876558, 2021). "As mRNA expression data were not available for these cohorts, INPP4B mRNA expression was examined using Tissue Scan Breast Cancer cDNA arrays I–IV (OriGene) of 130 primary human breast cancers and 16 normal breast tissues." (PMID 34035258, 2021). "In addition, INPP4B has been known to activate SGK3 and drive tumorigenesis in a subset of breast cancers with low levels of AKT." (PMID 29343273, 2018). "shRNA knockdown of INPP4B in MCF-7 and ZR-75-1 breast cancer cells, which express high levels of SGK3, reduced anchorage-independent cell growth, cell migration, 3D colony formation and mouse xenograft tumour growth as well as inhibiting IGF-1-stimulated SGK3 phosphorylation." (PMID 28082369, 2017). "The recent emergence of serum and glucocorticoid-regulated kinase (SGK3) as an oncogenic effector in PIK3CA-mutant breast cancer cells independent of AKT has led to the examination of INPP4B as a mediator of PI3K/SGK3 signalling." (PMID 28082369, 2017). "Authors have reported that INPP4B is expressed in nonproliferative estrogen receptor-(ER-)positive normal breast cells and breast cancer cell lines but not in ER-negative breast cancer cell lines." (PMID 22121480, 2012). "LGK-974 (PORCN inhibitor) rescued enhanced proliferation of INPP4B-overexpressing PIK3CA-mutant ER+ human breast cancer cells.Pyrvinium (CK1α inhibitor) reduced viability and 3D spheroid growth of INPP4B-overexpressing PIK3CA-mutant ER+ human breast cancer cells." (PMID 37471270, 2023). "Fittingly, INPP4B overexpression inhibits colony formation and anchorage-independent growth of human hepatocellular and cervical carcinoma cells lines as well as induced expression of INPP4B in human breast cancer cells without INPP4B expression reduced anchorage-independent growth." (PMID 36993823, 2023). "In order to assess whether INPP4B overexpressing ER+ breast cancer cells are sensitive to pyrvinium in 3D culture models, MCF-7 or T47D cells expressing GFP-vector or GFP-INPP4B were cultured in Matrigel for 4 days to form 3D spheroids, then treated with pyrvinium and/or 4-OHT for 72 h." (PMID 36612130, 2022).
breast carcinoma (continued). "Here, we show INPP4B overexpression does not affect the sensitivity of ER+ breast cancer cells to current standard-of-care therapies, but results in enhanced sensitivity to the FDA-approved Wnt inhibitor pyrvinium or 4-OHT-pyrvinium combination treatment in monolayer and 3D cultures." (PMID 36612130, 2022). "As INPP4B expression is increased in PIK3CA-mutant ER+ breast cancers where it promotes cell proliferation and tumor growth, we questioned whether INPP4B also affects the sensitivity of ER+ breast cancer cells to standard-of-care therapies." (PMID 36612130, 2022). "Interestingly, several recent reports have shown that INPP4B overexpression could be detected in other cancer contexts, such as PIK3CA-mutant breast cancer and a subset of melanoma." (PMID 29343273, 2018). "Also consistent is that protein levels of the mTOR pathway suppressors, PTEN and INPP4B, are relatively low in BLBC or TNBC patient tumors compared with other breast cancer subtypes; and mTOR pathway-related proteins, especially AKT and 4EBP1, show high phosphorylation levels in BLBCs." (PMID 24708766, 2014). "Although an earlier report showed that INPP4B could be downstream of ERα in breast cancer, there is no functional linkage and no pathophysiological characterization of how ERα could regulate this pathway to impact any type of cancer development." (PMID 25277204, 2014). "Although in one earlier report, INPP4B could be co-localized with ERα in luminal cells of breast cancer, yet there was no functional linkage and no pathophysiological characterization how ERα could regulate this INPP4B pathway to impact any type of cancer development." (PMID 25277204, 2014). "Reciprocally, knockdown of INPP4B increased both invasion and migration of the steroid receptor negative, basal-like MCF10A breast cancer cells, suggesting that INPP4B suppression of invasion is common in multiple cancer models." (PMID 25248616, 2014).